PGR (progesterone receptor)
Diseases named in the same sentence as PGR in open-access papers (continued):
Sharing a sentence is not in itself a finding about the gene and the disease.
tumor (continued). "Further, KLK15 is an independent prognostic factor of progression-free survival and overall survival in the subgroup of patients with lower grade and those with oestrogen receptor and progesterone receptor negative tumours in both univariate and multivariate analysis." (PMID 12439720, 2002). "However, none of the other variables, including tumour size, grade, histological type, Manchester score, axillary lymph node status, tumour oestrogen receptor, progesterone receptor, Ki 67 and epidermal growth factor receptor expression, correlated with ATase." (PMID 12087469, 2002). "Only two tumours were found to be true ER negative-PgR positive by all methods." (PMID 1616860, 1992). "c-erbB-2 staining was independent of age, tumour size, number of nodes involved, tumour grade and DNA ploidy, but was more common in oestrogen receptor (ER) negative tumours (P = 0.02) and progesterone receptor (PgR) negative tumours (P = 0.03)." (PMID 1672255, 1991). "However, the tumor cells were negative for estrogen receptor and progesterone receptor." (PMID 39415766, 2024). "Among all selected prognostic biomarkers, ESR1, PGR, BRTC, YWHAQ and PLK1 were recognized as crucial features; for clinical features, whether the patient has gone through chemotherapy/hormone therapy and the size of the tumor play an important role in model predictions." (PMID 36698767, 2023). "It is known that suppression is greater in tumours with high ER and PgR and in those negative for HER2 but the degree to which these relationships are independent of one another and of commonly measured clinico-pathological features could not be established in the modest sized studies to date." (PMID 37046348, 2023). "TNBC is characterized by a lack of expression of the estrogen receptor (ER) and progesterone receptor (PgR), and absence of human epidermal growth factor receptor 2 (HER2) protein overexpression; this type is known to have a poor prognosis and to recruit TILs and tumor-associated macrophages (TAMs)." (PMID 34089486, 2021). "Additionally, BCS + RT was less likely among patients diagnosed symptomatically, diagnosed during 2000–2004, had an unknown tumour grade, negative/unknown oestrogen and progesterone receptor status or tumour sizes ≥ 20 mm, ≤50 mm and had nodal involvement." (PMID 33800387, 2021). "BC may either show primary PgR negative phenotype (i.e., negative PgR expression in tumor sample assessed before systemic therapy), lose PgR expression during neoadjuvant treatment (assessed in the postsurgical specimen), or acquire PgR negative phenotype in local relapse or metastasis." (PMID 34638241, 2021). "Most interestingly, we suggest that ER- and PgR-positive tumor subtypes can be identified by a significantly increased abundance of TG ≥ C-48 with moderate or multiple unsaturated FA chains, which in contrast are significantly down-regulated in ER- and PgR-negative subtypes (HER2 and TNBC)." (PMID 32287294, 2020). "Importantly, although letrozole resistant cells had increased expression levels of ER, these tumor lines did not utilize estrogen for growth and had decreased amounts of the ER target gene PGR, further suggesting that they were using alternative pathways for growth." (PMID 27382432, 2016). "However, a few studies have suggested that the recurrence and death rate ratio is independent of PgR status in ER-positive (ER+) disease treated with adjuvant tamoxifen and that luminal A and B tumours similarly benefit from endocrine therapy regardless of PgR expression." (PMID 25938238, 2015). "Thus, we attempted to evaluate the prognostic role of PgR using a cut-off point of 20% and determine whether this threshold is appropriate to differentiate PgR-positive from PgR-negative disease and correctly elucidate the clinicopathologic features of ER+/PgR+/HER2- and ER+/PgR-/HER2- tumours." (PMID 25938238, 2015).
tumor (continued). "The rs3803662 genotype has been shown to associate most strongly with the ER/PgR positive and ERBB2 negative subgroups, which is the expression pattern of tumours of the luminal A subtype, further supporting that the effect seen in the BCAC study may be connected to luminal A tumours." (PMID 23270421, 2012). "In addition to being mostly high-grade tumours, a so-called triple negative phenotype (ER, progesterone receptor (PR) and HER2 negative), basal-type breast cancers may also have a characteristic central acellular or necrotic zone." (PMID 19165203, 2009). "In univariate analyses lymph node status (P=0.001), tumour size (P=0.002), and ER status were all inversely correlated with an event-free (distant recurrence) survival of patients longer than 240 months, whereas histological grade and type and the progesterone receptor status were not significant." (PMID 17299391, 2007). "Although traditional prognostic factors were well balanced (such as age, menopausal status and tumour size), other confounding factors such as progesterone receptor status were not balanced and the oestrogen receptor status is unknown in the patient population of three trials." (PMID 17325699, 2007). "The modest effect of the primary chemotherapy in ER positive tumours was noted by other investigators, who recently reported a much higher pCR rate with chemotherapy in ER/PgR negative patients and seems to suggest that aggressive chemotherapy should not be advisable in hormone-sensitive tumours." (PMID 17047649, 2006). "Tumor cells were positive for cytokeratin (CK), cytokeratin 7 (CK7), estrogen receptor (ER) and progesterone receptor (PR), but negative for Wilms' tumor 1 (WT‐1)." (PMID 41152971, 2025). "Immunohistochemically, the tumor was positive for vimentin, EMA, PgR, TTF-1, and somatostatin receptors-2, and negative for cytokeratin, Bcl-2, CD34, and S-100, with a Ki-67 index of approximately 5%." (PMID 40265140, 2025). "Immunohistochemical staining showed the tumor cells to be negative for Epithelial Membrane Antigen (EMA), positive for Vimentin (++), D2-40 (++), and negative for Progesterone Receptor (PR)." (PMID 40018446, 2025). "The blood vessels have a hemangiopericytomatous structure, and tumor cells express STAT6 but not SMA, estrogen receptor, or progesterone receptor." (PMID 41137250, 2025). "The profile of progesterone receptor-positive and -negative groups showed more MVs of neutrophils, endothelial cells, and HSP27+ tumor cells compared to the control." (PMID 40149564, 2025). "Immunohistochemistry results revealed that the tumor was positive for CD10, estrogen receptor (ER), progesterone receptor (PR), CD31, and CD34, while it was negative for CK-PAN, EMA, α-SMA, Desmin, Caldesmon, WT1, Calretinin, Inhibin α, SF1 and CD117." (PMID 41573257, 2025). "The various hormone receptor profiles showed the tumor was negative for CD5, CK5/6, c-kit, and p63, while positive for estrogen receptor (ER), progesterone receptor (PgR), and GATA-3." (PMID 41035587, 2025). "The tumor cells were immunoreactive for CD44, CD34, estrogen receptor (ER), and progesterone receptor (PgR), but negative for AE1/AE3." (PMID 41220004, 2025). "The tumor cells were focally positive for CK7, negative for CK20, CDX2, GATA-3, thyroid transcription factor (TTF-1), progesterone receptor (PR), SRY-related HMG-box (SOX-10), and mutant BRAF (V600E)." (PMID 39161498, 2024). "Immunohistochemistry of the right breast showed estrogen receptor (ER) negative, progesterone receptor (PR) negative, HER2 negative, and Ki67 immunoreactive in 25% of tumor cell nuclei." (PMID 39669282, 2024). "In this study, there were significant associations between high PTK7 protein expression and grade, higher NPI group, ER- or PgR-negative tumours, HER2-positive tumours, and triple-negative tumours." (PMID 39335176, 2024).
tumor (continued). "A significant negative correlation was observed between the percentage of progesterone receptor expression and SEMA3A expression in the tumor (p = 0.016, Spearman's R = − 0.25), but not in the vessels (p = 0.82)." (PMID 38263416, 2024). "We did, however, observe an association between PTK7 mRNA expression and the survival of patients with ER-positive (p = 0.020), PgR-negative (p = 0.002), and HER2-negative tumours (p < 0.001) in the METABRIC cohort." (PMID 39335176, 2024). "Tumour/liver SUVmax was higher in grade III patients (p=0.035) and progesterone receptor negative status (p=0.043)." (PMID 38164229, 2024). "Some oestrogen response genes (e.g. PGR) are still supressed in PRs ESR1HIGH, suggesting ER signalling is still functional in these tumours but not driving proliferation." (PMID 37419892, 2023). "Another research verifies this by revealing that the absence of KLF9 inhibits PGR and FOXO signaling in endometrial cells, boosting oncogenesis and Tumor spread." (PMID 37833790, 2023). "The tumor cells were positive for AE1/AE2, calretinin, WT-1, D2-40, HEG1, EMA, BAP1, and MTAP and negative for carcinoembryonic antigen, MOC-31, Ber-Ep4, ER, PgR, TTF-1, claudin 4, and desmin." (PMID 36896044, 2023). "NACT exerts the greatest potential in human epidermal growth factor receptor 2 (HER2) positive and triple-negative [estrogen receptor (ER) negative, progesterone receptor (PgR) negative, and HER2 negative] breast malignancies." (PMID 37441419, 2023). "Among these, TNBC is highly aggressive with absence of estrogen receptor (ER), progesterone receptor (PR), and HER2 on the tumor." (PMID 35326585, 2022). "Overall, the PDXs recapitulated the molecular subtype of the corresponding original tumor, with the exception of PDX284, which lacked the expression of progesterone receptor (PR) and became TNBC." (PMID 36071033, 2022). "Immunohistochemistry revealed that the tumor cells were positive for paired‐box gene 8 (PAX8), estrogen receptor (ER), and progesterone receptor (PR), but negative for thyroid transcription factor‐1 (TTF‐1)." (PMID 33300291, 2021). "High grade, high Ki67 labelling index, PgR-negative and HER2-positive tumours showed a significantly higher pCR rate (p = 0.017, p < 0.001, p = 0.033, and p = 0.001, respectively)." (PMID 34715905, 2021). "Unfortunately, due to insufficient tissue material, it was not possible to test the expression of the PgR and MGMT in the primary tumor, which are known predictors of efficacy of megestrol acetate and temozolomide, respectively." (PMID 33967965, 2021). "The tumor of origin of patient 3392 tests positive for Napsin A, and tests negative for estrogen receptor (ER), progesterone receptor (PR), WT1, and ARID1A, suggesting that the tumor was not of endometrial origin." (PMID 32784519, 2020). "Immunohistochemically, the tumor cells were positive for hepatocyte paraffin 1, AE1/AE3, and CD10 and negative for AFP, progesterone receptor, vimentin, chromogranin A, and synaptophysin." (PMID 31784920, 2019). "The tumor cells were positive for cytokeratin, nuclear/membranous β-catenin, CD10, and CD56 and were negative for chromogranin A, synaptophysin, progesterone receptor, vimentin, and Bcl-10." (PMID 31784920, 2019). "To analyze whether or not growth of triple-negative breast cancer (TNBC) or progesterone receptor-positive breast cancer (PR+BC) patient-derived xenografts (PDXs) causes oxidative stress, we evaluated the levels of 4-HNE in the hippocampal tissues of tumor-bearing mice." (PMID 29556248, 2018). "The increase in tumor volume was an unexpected result because SST-2 cells were identified as a triple negative cell line (estrogen receptor (ER)-negative, progesterone receptor-negative, and HER2-negative)." (PMID 29907135, 2018). "The CMT cells were positive for the epithelial marker, cytokeratin-8; tumor markers, VEGF, HER-2, MMP-2, HIF-1α, and Bcl-2; and hormone receptors, PGR and EPOR, while negative they were for estrogen receptor, ER." (PMID 30410940, 2018).
tumor (continued). "Tumors exhibiting a myoepithelial PAM50 profile are referred to as basal-like tumours and are usually triple negative breast cancers (TNBC) in that they do not express ESR1 and PGR and do not have amplified HER2 expression." (PMID 30248920, 2018). "On pathological examination, the tumor was a 1.4-cm IDC and surgical margins were negative, positive for ER and negative for PgR, HER2, and lymphatic vessel invasion, with an NG score of 1 and Ki67 of 30 %." (PMID 27256332, 2016). "Concordance was 100 % for ERBB2, ESR1, PGR whereas for MKI67, one case containing 10 % tumor cells was negative in the non-macrodissected sample." (PMID 27389414, 2016). "None of the variables markedly differed between patients with ER+/PgR purely negative/HER2- tumours and ER+/PgR<20%/HER2- tumours." (PMID 25938238, 2015). "The absence of progesterone receptor, TFF1 and especially TFF3 expression in patients with oestrogen receptor-positive tumours provides a strong indication that patients will not benefit from hormonal therapy." (PMID 25900183, 2015). "Using tumors 61–70 mm in size as the reference for estrogen receptor-negative (ER−) and progesterone receptor-negative (PR−) disease, the hazard ratio (HR) for BCSM increased with increasing tumor size across nearly all categories." (PMID 26036636, 2015). "Tumor heterogeneity, measured with HGRE, was higher in negative estrogen receptor (p = 0.039) and negative progesterone receptor tumors (p = 0.036), and in Scarff-Bloom-Richardson grade 3 tumors (p = 0.047)." (PMID 24722644, 2014). "Immunohistochemistry showed that these tumor cells were positive for desmin, smooth muscle actin, estrogen receptor, and progesterone receptor and negative for S100, CD117, and CD34, confirming the smooth muscle origin of the tumor." (PMID 24991446, 2014). "Tumor immunophenotype was determined for ESR1 (44 positive, 16 negative), PGR (35 positive, 25 negative), and ERBB2 (19 scored as negative or 1+, 11 scored as 2+, 11 scored as 3+ and 19 were not assayed)." (PMID 23936250, 2013). "Tumor HER2 receptors were negative; estrogen receptor (ER) and progesterone receptor (PgR) were positive." (PMID 23424693, 2013). "Studies on immunohistochemical analysis of these tumours have revealed that all these tumours are oestrogen receptor positive, HER2 negative whereas most are progesterone receptor positive." (PMID 24066247, 2013). "Strikingly, FMR1 mRNA expression was increased with a high statistical significance in the more aggressive TNBC subtype (i.e. ER/PgR and HER2 negative) compared to the ER/PgR and/or the HER2 positive tumours." (PMID 24092663, 2013). "Triple-negative (ER = 0%, PgR = 0%, HER2-negative) pT1a-pT1 b tumours were 26 (6.5%); 2 were pT1a and 24 were pT1b." (PMID 22545982, 2012). "These labeling patterns are seen in tumors expressing various combinations of HER2, estrogen receptor, and progesterone receptor, suggesting that stromal NG2 expression is relatively independent of the receptor profile of the tumor." (PMID 22531600, 2012). "Patients in the YKL-40 negative tumor group, but not in the YKL-40 positive group, who expressed the progesterone receptor had higher levels of serum YKL-40 (P<0.05)." (PMID 23227243, 2012). "Immunohistochemically, the tumor cells were widely positive for vimentin, CD56, CD99 and focally positive for synaptophysin, CD10, progesterone receptor, desmin and CD34, but negative for EMA, cytokeratin, estrogen receptor, S-100, GFAP and myoglobin." (PMID 23217062, 2012).
tumor (continued). "PgR positive tumours also had significantly higher TOX3 and LOC643714 mRNA levels than PgR negative ones (p = 0.005 and p < 0.001, respectively)." (PMID 23270421, 2012). "The risk allele of rs3803662 was highly correlated with a subgroup of basal tumours that expresses EGFR and CK5/6 but not ER, PgR and ERBB2." (PMID 23270421, 2012). "Immunohistochemically, the tumor cells were widely positive for vimentin, CD56, CD99 and focally positive for synaptophysin, CD10, progesterone receptor, desmin and CD34, but negative for EMA, cytokeratin, estrogen receptor, S-100 and myoglobin." (PMID 23217062, 2012). "The tumor was staged as T1N0M0 and was estrogen receptor (ER)- and progesterone receptor (PR)-negative." (PMID 21896177, 2011). "The tumor cells were positive for EMA and S-100 protein and focally positive for cytokeratin and ER but negative for progesterone receptor, CD34, and CEA." (PMID 22332016, 2011). "The tumours positive and negative for ER, PR and HER2 showed a significantly different level of expression for their respective genes ESR1, PGR and ERBB2 (P<0.01, Welch's t-test)." (PMID 22067903, 2011). "Patient age (P=0.65), tumour size (P=0.7), histological subtype (P=0.58), tumour grade (P=0.112), HER2 status (P=0.354), progesterone receptor status (P=0.116) and Ki67 (P=0.71) did not predict response to anthracycline-based therapy." (PMID 21063406, 2010). "In case of a co-expression of HR and HER2 the tumor was included in the HR+/HER2+ category (13 cases, 11.2%), while tumors negative for ER, PgR and HER2 were designated as HR-/HER2- (triple negative, 33 cases, 28.4%)." (PMID 19758440, 2009). "In the HER2-negative cohort, one patient experienced a durable CR (23 weeks) and had a primary tumour with the following molecular characteristics: HER2 negative and EGFR negative; ER positive and PgR positive; low expression of PTEN and PIK3CA (E767K) SNP." (PMID 19844234, 2009). "The tumor cells were negative for Gross cystic disease fluid protein (GCDFP), estrogen (ER) and progesterone receptor (PR)." (PMID 17324295, 2007). "Total and free VEGF levels were significantly higher in ER-negative tumours, and free VEGF levels were also higher in PgR-negative tumours." (PMID 15668703, 2005). "In their subsequent study involving 184 tumours of node-negative patients, no significant relation between PMN-E and ER or PgR was found." (PMID 12671709, 2003). "It is interesting that 90% of the patients with an oestrogen receptor negative, MMP-2 negative or 95% of the patients with a progesterone receptor negative, MMP-2 negative primary tumour were alive after the 10 years of the follow-up." (PMID 14520459, 2003). "Conversely, progesterone receptor (PR) was negative in the only tested case, as well as GATA-3, SALL-4, PTEN, PAX-2, AFP and calretinin, while ARID1A was retained in one case and another tumor has a CK7+/CK20− phenotype." (PMID 39996865, 2025). "High expression of PTK7 mRNA was significantly associated with higher NPI group (χ2 = 38.023, d.f. = 2, p < 0.001), ER-negative tumours (χ2 = 203.406, d.f. = 1, p < 0.001), PgR-negative tumours (χ2 = 69.697, d.f. = 1, p < 0.001), and HER2-positive tumours (χ2 = 38.726, d.f. = 1, p < 0.001)." (PMID 39335176, 2024). "Large, aggressive tumours and advanced stage cancer were more frequent in the PABC group with overexpression of human epidermal growth factor receptor 2 [HER2] and oestrogen receptor negative and progesterone receptor negative status." (PMID 38694578, 2024). "Typically characterised by a lack of oestrogen receptor (ER), progesterone receptor (PR) and human epidermal growth factor receptor 2 (HER2), TNBC is characterised by a higher degree of aggressiveness, tumour burden and poorer prognosis compared with other subtypes." (PMID 39550706, 2024).